CPT1C (carnitine palmitoyltransferase 1C)
Diseases named in the same sentence as CPT1C in open-access papers (continued):
Sharing a sentence is not in itself a finding about the gene and the disease.
tumor (continued). "In addition, recent research has demonstrated that CPT1C exerts control over the proliferation and senescence of tumor cells by regulating lipid metabolism and mitochondrial function." (PMID 38012244, 2023). "Furthermore, stearate and oleate are involved in CPT1C-mediated tumor cell proliferation and senescence." (PMID 37151873, 2023). "Interestingly, Palomo–Guerrero and collaborators demonstrate that CPT1C regulates protrudin function depending on malonyl-CoA levels, suggesting that CPT1C can modulate tumor invasion depending on nutrient availability." (PMID 36693836, 2023). "Moreover, tumor-bearing mice subjected to chronic hypoxia showed an increase in CPT1C expression in the tumor mass." (PMID 36693836, 2023). "In addition, stearate and oleate were found to be involved in CPT1C-mediated tumor cell proliferation and senescence." (PMID 37151873, 2023). "Moreover, stearate and oleate play a vital role in CPT1C-mediated tumor cell proliferation and senescence." (PMID 37151873, 2023). "Recently, Bi’s group has discovered that PPARα, a ligand-activated transcription factor that regulates lipid metabolism and tumor progression, also activates CPT1C expression by binding directly to the promoter region of CPT1C, indicating that CPT1C is a novel downstream target gene of PPARα." (PMID 36693836, 2023). "Furthermore, interference of CPT1C expression significantly prolonged the survival of the orthotopic tumor mouse models (left)." (PMID 35936710, 2022). "Furthermore, interference of CPT1C expression impairs tumor growth and pulmonary colonization of BLBC cells in vivo, and even postpones the occurrence of spontaneous metastasis, resulting in a prolonged disease-specific survival (DSS)." (PMID 35936710, 2022). "Overall, expression of CPT1c in tumor cells increases significantly." (PMID 34925039, 2021). "Moreover, the tolerance of tumor cells with high expression of CPT1c to ischemia and hypoxia is significantly enhanced, and inhibiting expression of CPT1c has the opposite effect." (PMID 34925039, 2021). "In addition, it is necessary to explore how this altered action of miR-1291 affects the fate of tumor cells after the existence of the miR-1291-ERRα-CPT1C axis is confirmed." (PMID 32641987, 2020). "Therefore, the objective of the current study was to dissect the regulatory mechanism of the miR-1291-ERRα-CPT1C axis and to explain how each synergistically works on tumor cell metabolism and proliferation." (PMID 32641987, 2020). "Therefore, it is necessary to explore how ERRα and CPT1C, two known key molecules that can respectively affect the proliferation and metabolism of tumor cells, play an important role in the action of miR-1291." (PMID 32641987, 2020). "Finally, a recent study revealed that peroxisome proliferator-activated receptor alpha (PPARα) upregulated the expression of CPT1C, in a p-53 independent way, modulating proliferation and senescence of tumor cells." (PMID 29445084, 2018). "Interestingly, depletion of CPT1C in mice led to delayed tumor development and a striking increase in survival." (PMID 29445084, 2018). "Additionally, CPT1C allows tumor cells to survive in hypoglycemic and hypoxic conditions, while CPT1C silencing leads to delayed tumor development." (PMID 29725060, 2018). "Indeed, a specific isoform of carnitine palmitoyltransferase (CPT1C) is frequently upregulated in human lung tumours, and perturbation of CPT1C reduced the growth of tumour xenografts and rendered cells more sensitive to metabolic stress." (PMID 28106780, 2017). "Nearly all of these mutations resulted in amino acid changes in well-known metabolic genes such as LDHB (which is important in glycolysis for the conversion of lactate and pyruvate), TRIT1, which has been proposed as a tumour suppressor and CPT1C, important in fatty acid metabolism." (PMID 28163917, 2017).
tumor (continued). "A recent study showed that CPT1C is frequently upregulated in human lung tumor and that CPT1C depletion via siRNA suppresses xenograft tumor growth in vivo, suggesting that CPT1C may be a new therapeutic target for the treatment of hypoxic tumors." (PMID 22533991, 2012). "Although the precise role of CPT1 in tumor growth remains unknown, a recent study showed that CPT1C is frequently expressed in tumors and up-regulated in response to metabolic stress." (PMID 22533991, 2012). "Consequently, future investigations may be directed towards elucidating the tumor-promoting mechanism of CPT1C in BLCA patients and evaluating the prognosis of its targeted drugs in improving the prognosis of BLCA patients." (PMID 38012244, 2023). "However, the relationship between CPT1C and fatty acid metabolism during tumor cell senescence remains unknown." (PMID 37151873, 2023). "In addition, CPT1C promotes ATP production from FAO to protect tumor cells from metabolic stress." (PMID 35936710, 2022). "Thus, the miR-1291-ERRα-CPT1C axis could coordinate with the synergistic regulation of tumor cell proliferation and metabolism, and the combination of miR-1291 with other drugs or treatment methods related to ERRα and CPT1C may be possible." (PMID 32641987, 2020). "Interestingly, CPT1C is only expressed in neurons and tumor cells in mammals." (PMID 29725060, 2018). "Furthermore, CPT1C depletion reduced tumor growth in xenograft models." (PMID 22533991, 2012). "Results show that low CPT1C expression was related to poorer RFS rates only for tumours with high HER2 expression and tumours with low ERα, Erβ, and PR expression." (PMID 36674468, 2023). "Carnitine palmitoyltransferase 1C (CPT1C) has been described as a poor-prognosis marker for several tumour types, as it favours tumour growth and hinders cells from entering senescence." (PMID 36674468, 2023). "To define the role of the miR-377-3p/CPT1C axis in vivo, we established xenograft mouse model to evaluate the impact of the axis on HCC tumor growth." (PMID 35057851, 2022). "CPT1C-KD (MDA-MB-231-siCPT1C#3) and its control cells were inoculated into the mammary fat pad, and the tumor size was measured every three days for five weeks." (PMID 35936710, 2022). "Moreover, miR-377-3p decreased fatty acid oxidation by inhibiting CPT1C and thereby modulated cell proliferation, migration and invasion in vitro and in vivo, suggesting another signaling pathway for miR-377-3p in regulating tumor occurrence and progression in HCC." (PMID 35057851, 2022). "The expression level of CPT1C did not correlate significantly with the following clinical features: sex, age, tumor size, lymph node, metastasis, grade, or tumor-node-metastasis (TNM) stage (P > 0.05)." (PMID 38783346, 2024). "The study confirmed that CPT1C is a novel target gene of PPARα, and that knockout of PPARα leads to a decrease in CPT1C expression, which inhibits the proliferation of MDA-MB-1 and PANC-1 tumor cell lines in a CPT1C-dependent manner." (PMID 37251321, 2023). "To determine whether miR-377-3p and CPT1C expression had clinical significance, we collected 90 pairs of HCC tumor and adjacent normal samples." (PMID 35057851, 2022). "All these data suggest that enhanced expression of CPT1C by HIF-1α might support tumor progression by other ways nonrelated to FAO." (PMID 36693836, 2023). "CPT1C overexpression in hMSCs did not increase fatty acid oxidation capacity, indicating that the role of CPT1C in these cells is different from that described in tumor cells." (PMID 29725060, 2018). "Additionally, it is uncertain whether CPT1C influences tumor progression via non-FAO pathways in brain metastases." (PMID 41219902, 2025).
neurological disorders (1 paper, 2022). "Moreover, we identified 3 upregulated [ENO3, LPIN1 and SCN9A] and 3 downregulated [ATL3, CPT1C, and SGCB] RNAs whose genes have been implicated in neurological disorders." (PMID 34907471, 2022).
CPT1C also shares sentences with these, for which no sentence is quoted: Hepatic steatosis (3 papers); metabolic disorder (3); brain tumors (2); colon cancer (2); diabetes (2); hyperlipidaemia (2); infection (2); Insulin resistance (2); leukemia (2); long chain acyl-CoA dehydrogenase deficiency (2); type 2 diabetes (2); Anorexia (1); Anxiety (1); Ataxia (1); bone sarcoma (1); brain cancer (1); breast tumours (1); carnitine deficiency (1); carnitine-acylcarnitine translocase deficiency (1); chronic lymphocytic leukemia (1); fasciolosis (1); genetic disorder (1); glioblastoma (1); hemosiderosis (1); hereditary spastic paraplegia type 73 (1); hypothyroidism (1); microencephaly (1); neurofibroma (1); ovarian carcinoma (1); ovarian tumor (1).
A further 4 diseases each share a sentence with CPT1C in 1 paper.